CRP (C-reactive protein)
Diseases named in the same sentence as CRP in open-access papers (continued):
Sharing a sentence is not in itself a finding about the gene and the disease.
pneumonia (continued). "This study found a positive correlation between age, ADL, white blood cells, percentage of neutrophils, C-reactive protein, and pneumonia." (PMID 39398953, 2024). "This makes it a practical option for screening and monitoring pneumonia compared to complex or expensive biomarkers, such as CRP, IL-6, and TNF-a." (PMID 38404841, 2024). "In some cases, elevated CRP levels led to the diagnosis of serious infections, such as pneumonia or spondylodiscitis, while decreased eGFR levels prompted additional nephrology consultations and modifications in medication management." (PMID 39594253, 2024). "White blood cells, neutrophils, eosinophils, basophils, PCT, CRP, and pneumonia type are also correlated." (PMID 39188873, 2024). "The high rate of pulmonary infiltrates among inpatients, along with a significantly higher level of C-reactive protein, suggests bacterial superinfection/pneumonia as a possible mechanism for the more severe course of the disease." (PMID 39331940, 2024). "Given the current research status, we believe that dynamic detection of CRP, PCT, blood routine, IL-6, and SAA in high-risk children is helpful for assessing the severity of pneumonia." (PMID 39411281, 2024). "Serum CRP levels were found to be significantly correlated with severe pneumonia and bacterial infections." (PMID 39727640, 2024). "Her medical history was remarkable for recurrent hospitalizations due to pneumonia with high erythrocyte sedimentation rates (range: 74-120 mm/hr) and C-reactive protein levels (range: 6-47 mg/L)." (PMID 38578569, 2024). "In most studies on pneumonia with bacterial coinfection, elevated CRP and procalcitonin levels have been observed." (PMID 38475703, 2024). "A 4-month-old girl with pneumonia, elevated CRP (282 mg/L), anemia (8 g/dL) and severe neutropenia (200/μL) was referred to our hospital." (PMID 39286252, 2024). "Studies on the association between clinical severity scores for pneumonia, such as CURB65 and PSI, with biomarkers like CRP (C-reactive protein), procalcitonin (PCT), and suPAR (soluble urokinase plasminogen activator receptor) show varied results." (PMID 39182045, 2024). "In case of pneumonia suspicion with a CRP level under 130 mg/L (independently of the severity) L-UAT is useless in immunocompetent patients with a NPV at 100%." (PMID 38530466, 2024). "The high CRP levels can be utilized to the early diagnosis of the severe lung infections in the patients with severe pneumonia." (PMID 38741671, 2024). "The calculated cutoff point for CRP was determined to be 40.8 mg/dL, achieving a sensitivity of 56% and specificity of 87% in diagnosing pneumonia." (PMID 38910264, 2024). "(ii) Severe pneumonia cases with C-reactive protein (CRP) more than 35 mg/L were encountered mainly in the Adv group, while CRP ≤ 35 mg/L was mainly in the RSV group, and the difference was statistically significant with p = 0.012 and χ2 = 8.795." (PMID 38543775, 2024). "Regardless of this, we found a weak but positive correlation of uCRP with bCRP, which was also shown in one of the rare studies that explored CRP in both urine and blood samples in patients with pneumonia." (PMID 39309742, 2024). "The ROC-Curve of the different sub-populations of Besançon University Hospital patients confirmed that CRP levels can be also used in patients with pneumonia (AUC 82.3%; 95% CI, 72.0–92.7) and critical patients (AUC 93.0%; 95% CI, 87.1–99.0)." (PMID 38530466, 2024). "The major clinical symptoms of these patients showed fever, chills, headache, eschar, fatigue and pneumonia, which were accompanied by a rise in C-reactive protein, neutrophils, alanine transaminase (ALT) and aspartate aminotransferase (AST)." (PMID 38442086, 2024). "Logistic regression analysis of post-transplant pneumonia occurrence indicated that lower post-transplant vitamin D levels and higher post-transplant CRP levels were significant covariates." (PMID 39524045, 2024).
pneumonia (continued). "The combined detection of CRP and LDH helps predict the risk of PE in children with plastic bronchitis caused by pneumonia." (PMID 39513159, 2024). "The association (Spearman’s correlation coefficient) between the four mentioned categories of CRP changes and pneumonia with different extents of hypoxia." (PMID 39064460, 2024). "Two weeks later, hospitalised due to pneumonia, fever, CRP 100 and diagnosed with febrile neutropenia." (PMID 38926298, 2024). "Based on this, this study aims to explore the effects of NAC combined with AH in the treatment of pediatric pneumonia regarding the regulation of clinical symptoms, C-Reactive Protein (CRP), and Procalcitonin (PCT) levels." (PMID 39208656, 2024). "Procalcitonin and CRP can also aid in early-stage pneumonia prognosis prediction and pneumonia severity." (PMID 39727640, 2024). "Among the 175 patients diagnosed with pneumonia, 19 (11%) had fever at first measurement, median CRP was 87 mg/L (IQR 32–157), neutrophil leucocyte count was 7.4 × 109/L (IQR 4.8–10.2), and median oxygen saturation was 94% (IQR 92–96%)." (PMID 37572241, 2024). "Higher CRP and lower oxygen saturation were independent variables for predicting the development of pneumonia." (PMID 38475703, 2024). "Elevated CRP levels in pneumonia patients often indicate a more aggressive inflammatory response and a higher burden of infection." (PMID 38167637, 2024). "The discovery of CRP by Francis was pivotal in diagnosing and tracking illnesses like pneumonia and rheumatic fever, as it served as an early sign of infection." (PMID 39726515, 2024). "Elevated CRP levels on specific postoperative days correlate with complications including pneumonia, wound infection, and leakage." (PMID 39598263, 2024). "The present study aimed to evaluate the levels of CRP in severe measles complicated by primary morbillous pneumonia with various degrees of respiratory insufficiency and to determine its potential utility as a predictor of the severity of morbillous infection." (PMID 39064460, 2024). "One study reported the discriminatory capabilities of CRP with AUCs of 0.81 for serious bacterial infection and 0.43 for mortality in children presenting with suspected meningitis or pneumonia." (PMID 39015209, 2024). "The findings revealed that the CRP concentration exhibited substantial discriminatory power for distinguishing between pneumonia patients and controls (AUC = 0.78, p < 0.001)." (PMID 38910264, 2024). "When treating pneumonia patients, serum CRP can help differentiate between endobronchial and parenchymal infections." (PMID 39727640, 2024). "The clinical significance of CRP was evident, as it served as a valuable marker for assessing the presence of acute infections and inflammatory conditions, from pneumonia to rheumatic fever and other systemic inflammatory diseases." (PMID 39726515, 2024). "Two prospective longitudinal cohort studies found that CRP levels were lower in children with pneumonia three days before symptoms appeared, suggesting that CRP testing after three days was more meaningful in assessing disease severity." (PMID 39411281, 2024). "A study showed that serum presepsin levels were significantly correlated with procalcitonin, lactate, C-reactive protein, pneumonia severity index, and fast sequential organ failure assessment (qSOFA)." (PMID 39727640, 2024). "Back to the nature of the CAR, many previous studies had demonstrated the role of CRP and albumin in predicting pneumonia." (PMID 38685951, 2024). "An inflammatory response defined as an elevated leucocyte count and elevated C-reactive protein (CRP) was more likely to appear in pneumonia cases than bronchiolitis." (PMID 39314554, 2024). "Regarding the mediating pathways between WC and pneumonia, CRP, IL-6, and FEV1 mediated 26.90% (95% CI: 13.98%, 39.83%), 10.23% (95% CI: 2.72%, 17.73%), and 4.67% (95% CI: 0.25%, 9.09%) of the effect of WC on pneumonia, respectively." (PMID 39337223, 2024).
pneumonia (continued). "Serum C-reactive protein (CRP) is an acute-phase reactant that can be raised in commonly encountered pulmonary disorders like pneumonia, malignancies, and pulmonary thromboembolism." (PMID 39205740, 2024). "For other POCTs, patients satisfying disease criteria based on the test results were supposed to be prescribed amoxicillin for pneumonia, antibiotics for CRP levels greater than or equal to 100 mg/l, or zinc sulfate tablets for non-bloody diarrhoea." (PMID 37612636, 2023). "Especially in children over two years of age with RSV, high CRP levels can be a helpful parameter in the planning of the treatment process for patients diagnosed with pneumonia and LRTI in the emergency department." (PMID 37376545, 2023). "Multivariate regression analysis extracted older age, elevated CRP and lower eosinophil count as significant independent predictors of pneumonia (p = 0.003, p = 0.000, p = 0.046, respectively)." (PMID 37570378, 2023). "Blood testing showed rapid decreases in the levels of CRP and IL-6, and imaging tests showed the resolution of pneumonia." (PMID 37124420, 2023). "Blood testing showed elevated levels of CRP and interleukin (IL)-6, and CT showed worsening pneumonia." (PMID 37124420, 2023). "Inflammatory markers such as CRP and Procalcitonin were significantly higher in the pneumonia group than the non-pneumonia group." (PMID 37763972, 2023). "This review focuses mainly on PCT and CRP, since they are the most studied and most used biomarkers in daily clinical practice in the management of patients with pneumonia, given their clinical utility, low cost, and easy availability elsewhere." (PMID 36671362, 2023). "The first wave accounted for 1823 (33%) admissions and exhibited the highest proportion of severe patients: 65% with bilateral pneumonia and 83% with oxygen saturation under 94% during admission and elevated levels of CRP, IL-6, and D-dimer." (PMID 37766248, 2023). "By multivariate analysis, pleural effusion was found to be an independent negative prognostic factor compared with other variables such as increased C-reactive protein, greater extent of pneumonia and older age." (PMID 36769697, 2023). "In influenza pneumonia few studies have been designed with the aim of evaluating the prognostic value of CRP." (PMID 36671362, 2023). "Based on the covariate balancing propensity scores, the two groups were matched using the covariates of age, gender, BMI, the coexistence of pneumonia, albumin level, CRP, and lymphocyte count, and 37 patients were selected from each group." (PMID 37240466, 2023). "In our study, the measurement of CRP and the time to diagnose pneumonia-related bacteremia differed from previous findings." (PMID 37768395, 2023). "All RV-positive children with pneumonia had high white blood cell counts, plasma C-reactive protein or procalcitonin levels, or alveolar changes in chest radiograph strongly indicating bacterial infection." (PMID 37009280, 2023). "Univariate logistic regression analysis showed that severe group, WBC count, lymphocyte count, neutrophil count, LDH, CRP, SAA, HS-TnT, albumin, CKMB_M, myoglobin, and sodium were significantly associated with remission of pneumonia (all p < 0.05)." (PMID 37965268, 2023). "Potential mechanisms linking baseline levels of CRP, GDF-15 and MMP-8 to pneumonia risk require further study." (PMID 38105941, 2023). "Together with an assessment of other clinical parameters, however, the CRP level is an important predictor of severe ARTI (pneumonia, sepsis)." (PMID 37900677, 2023). "In an RCT that enrolled 46 patients with COVID-19-associated pneumonia, the NAC (1,200–1,500 mg IV)-treated group showed a significant increase in blood oxygen saturation and CRP values and a decrease in hospital stay." (PMID 37534078, 2023).
pneumonia (continued). "In our study, 362 patients (37%) had radiological findings (chest CT or chest X-ray) characteristic of pneumonia, and regression analysis showed a highly significant OR of initiation of antibiotic treatment, in addition to CRP level > 60 mg/L." (PMID 37107150, 2023). "As an important marker of the inflammatory process, CRP has a value in the diagnosis of pneumonia to some extent." (PMID 37296721, 2023). "Two of the evaluation score factors were significantly more often found in patients prescribed antibiotics: signs of pneumonia in chest X-ray/CT (OR 3.66 (95% CI 2.40–5.58, p < 0.001) and CRP level >60 mg/L (OR 4.69 (95% CI 3.12–7.04, p < 0.001)." (PMID 37107150, 2023). "In England, although the 2014 NICE guideline on pneumonia recommended the use of CRP POC tests in the management of adults with suspected pneumonia, these had limited impact in terms of their implementation in GP practices." (PMID 36823597, 2023). "In a previous study, we reported that the salivary CRP levels in children with pneumonia were highly correlated with the serum CRP levels." (PMID 37189569, 2023). "In another report from Singapore, there were correlations between antibody responses against the N4P5 epitope and pneumonia and the tissue damage markers CRP and lactate dehydrogenase." (PMID 37110438, 2023). "Pneumonia patients had considerably greater white blood cell counts, C-reactive protein levels, and procalcitonin levels than control subjects." (PMID 36923935, 2023). "All patients with serious infections had elevated white blood cells count, CRP and X-ray results consistent with severe bilateral pneumonia." (PMID 36678465, 2023). "In England, one guidelines from the National Institute for Health and Care Excellence (NICE) recommends the use of CRP POC tests in adults with suspected pneumonia which is similar to the Dutch guidelines." (PMID 36823597, 2023). "Malnourished children with pneumonia had significantly higher values of leukocytes, absolute neutrophilic count, and C-reactive protein, and lower values of hemoglobin, lymphocytic count, platelets, and albumin, compared to controls, respectively." (PMID 37542670, 2023). "In our study, we did not include the body temperature, inflammatory markers (e.g., C-reactive protein), or the extent of radiological findings of pneumonia." (PMID 36792635, 2023). "In a previous study, we showed that salivary C-reactive protein (CRP) levels were highly correlated with serum CRP levels in pediatric patients with pneumonia." (PMID 37189569, 2023). "Median CRP was higher in patients with pneumonia: 69 (IQR 32 to 129) mg/L versus 35 (IQR 10 to 96) mg/L (p = 0.03)." (PMID 37115214, 2023). "C-reactive protein (CRP) is released during inflammatory events; therefore, CRP levels correlate with disease severity, lung function, volume alterations and pneumonia development." (PMID 37371870, 2023). "With regards cost-effectiveness, studies also suggest that the use of CRP POC tests is cost-effective in the pathway of care for adults with pneumonia in both countries." (PMID 36823597, 2023). "The inflammatory indexes of serum procalcitonin (PCT) and C-reactive protein (CRP) levels were significantly higher in the patients with KP-pneumonia/KP-BSI than in the patients with KP pneumonia alone." (PMID 36978069, 2023). "The univariate analysis showed that the gestational age, pneumonia, leukocytes, lymphocytes, erythrocytes, platelets, C-reactive protein, and blood glucose were statistically significant in the surgical group compared to the conservative group (All P < 0.05)." (PMID 37576139, 2023). "It was also noted that the NLR value had a positive correlation with the assessment of the severity of pneumonia, length of hospital stay, and CRP and D-dimer levels." (PMID 36975366, 2023). "CRP was first discovered in sera from pneumonia patients in 1930, when it was shown to precipitate the C-polysaccharide of Streptococcus pneumoniae." (PMID 37275364, 2023).
pneumonia (continued). "For example, CRP was better than PCT at predicting pneumonia, as demonstrated in a retrospective study of elderly patients with comorbid diseases." (PMID 37296721, 2023). "Serum CRP is sensitive to infection and inflammation and was revealed to be correlated with the survival of pneumonia patients that received antibiotic therapy and to predict the prognosis of CAP." (PMID 37291525, 2023). "Attention to the presence of pneumonia, changes in CRP, and lymphocyte levels in neonates with NEC, combined with indicators such as clinical manifestations, is potentially significant in predicting the need for surgical intervention and their prognosis." (PMID 37576139, 2023). "Univariate logistic regress analysis of factors affecting progression to severe pneumonia showed that the use of Thymalfasin was a protective factor, while elevation of WBC, PCT and CRP was a risk factor." (PMID 37743481, 2023). "Secondary outcomes included the hospital length of stay (LOS), the concentrations of ferritin, C-reactive protein and albumin, oxygen requirements and the severity of pneumonia." (PMID 36986138, 2023). "For PD, C-reactive protein (CRP) plasma concentrations were described by transit compartments and were found to decrease with the presence of pneumonia." (PMID 37876732, 2023). "Further, the multivariate logistic regression analysis suggested both S1P and CRP are independent predictors for COPD patients with pneumonia." (PMID 35307030, 2022). "In this study, the results of c-reactive protein (CRP) blood tests contributed more than physical examination parameters to the diagnosis of pneumonia." (PMID 36303104, 2022). "Due to severe bacterial infection status, the CRP level is usually very high in patients with severe pneumonia." (PMID 35307030, 2022). "Consistent with this literature, we found that in this subset of patients hospitalized with pneumonia, CRP and D-dimer levels were high in all subjects (albeit the measures were somewhat higher in the D30 group and the D40 group than in the D50 group)." (PMID 36014757, 2022). "Our goal was to assess the feasibility and safety of an individualized, biomarker-guided corticosteroid dosing approach utilizing C-reactive protein (CRP) in patients with pneumonia and acute hypoxemic respiratory failure (AHRF)." (PMID 34983600, 2022). "As expected, pneumonia lung injury characterized by computer tomography (CT) positively correlated with levels of CRP, D-dimer, and neutrophils/lymphocytes ratio." (PMID 36012146, 2022). "Logistic regression analysis worked out a model composed of items on dyspnea, respiration rates > 20/min, and CRP > 20 mg/l (DRC) for pneumonia prediction with an area under curve (AUC) of 0.8506." (PMID 36253753, 2022). "A Cochrane review from 2014 evaluated the contribution of the point of care (CRP) test for appropriate use of antibiotics for pneumonia." (PMID 36303104, 2022). "Two biomarkers, C-reactive protein and procalcitonin, in addition to other features, were considered very important in the prediction of pneumonia." (PMID 35968461, 2022). "They further suggested utilizing CRP/NPT ratio in serum to discriminate pneumonia from AECOPD in COPD patients." (PMID 35307030, 2022). "Despite the statistically insignificant difference (P = .09), the positive rate of CRP was found to be high in patients with clinical signs and symptoms of pneumonia." (PMID 35784807, 2022). "WBC, PCT and CRP has been widely tested to detect postoperative pneumonia, but its effectiveness is still controversial." (PMID 35794529, 2022). "In mice infected with S. pneumoniae-induced pneumonia, the inhibition of miR-497-3p significantly attenuated the expression levels of C-reactive protein (CRP) and inflammatory cytokines in the lung tissues." (PMID 35986232, 2022).